KIR2DP1 (killer cell immunoglobulin like receptor, two Ig domains pseudogene 1)
Synonyms: KIRZ; KIRY; KIR15; KIR2DL6
Gene: Unprocessed pseudogene on chromosome 19 (54,755,023 to 54,767,371, forward strand). Ensembl gene ENSG00000242473.
Diseases named in the same sentence as KIR2DP1 in open-access papers:
KIR2DP1 is named in the same sentence as 2 diseases in open-access papers, as found by Europe PMC text mining. Sharing a sentence is not in itself a finding about the gene and the disease.
KIR2DP1 shares sentences with these, for which no sentence is quoted: Diabetes (1 paper); malaria (1).